CAGE1 (cancer antigen 1)
Synonyms: CT3; CTAG3; bA69L16.7; CT95
Tractability: No criterion of Open Targets' tractability assessment is met for any kind of drug.
Gene: Protein-coding gene on chromosome 6 (7,326,656 to 7,389,742, reverse strand). Ensembl gene ENSG00000164304.
Gene Ontology:
Molecular function: protein binding
Genetic constraint (gnomAD): Loss-of-function variants: 37 observed, 61.43 expected, observed/expected ratio (o/e) 0.6, 90% interval 0.46 to 0.79. The upper end of that interval is the gene's LOEUF score, 0.79, which puts it in group 3 of 6, group 1 being the genes least tolerant of losing a copy. Missense variants: 618 observed, 720.5 expected, observed/expected ratio (o/e) 0.86, 90% interval 0.8 to 0.92. Synonymous variants: 244 observed, 254.37 expected, observed/expected ratio (o/e) 0.96, 90% interval 0.86 to 1.07.
Homologues: Orthologues: chimpanzee CAGE1 (99% identical), macaque CAGE1 (92% identical), rabbit CAGE1 (61% identical), guinea pig CAGE1 (58% identical), mouse Cage1 (57% identical), rat Cage1 (56% identical), dog CAGE1 (54% identical), pig CAGE1 (51% identical).
Diseases named in the same sentence as CAGE1 in open-access papers:
CAGE1 is named in the same sentence as 24 diseases in open-access papers, as found by Europe PMC text mining. Sharing a sentence is not in itself a finding about the gene and the disease. The quoted sentences say what the papers report.
breast carcinoma (4 papers, 2007 to 2022). "Of 16 CTAGs examined in the first panel of 42 breast cancer samples, seven antigens were found not to be expressed in any of the specimens: SSX2, SSX4, CTAG2, CAGE1, MAGEA1, MAGEA4 and MAGEA11." (PMID 17650306, 2007).
rosacea (1 paper, 2021). A chronic erythematous skin disorder that affects the face. "Mechanistically, CAGE1:2 appeared to target two key pathways know in rosacea." (PMID 34027084, 2021).
tumor (10 papers, 2012 to 2025). "Emerging studies have revealed that numerous CTAs, such as SSX (CTA5), CAGE-1 (CTA3), Piwil2 (CTA80), CT45A1, and the MAGE family gene MAGE-C2 (CTA10), induce EMT to promote tumor metastasis." (PMID 35347116, 2022).
cancer (9 papers, 2020 to 2025). A tumor composed of atypical neoplastic, often pleomorphic cells that invade other tissues. "Similarly, CAGE1, a gene widely associated with cancer was significantly upregulated in the GFP-KDEL cells, while it was significantly downregulated in SUN1L-KDEL cells illustrating an opposite pattern of response of the gene FSIP2 to LINC disruption." (PMID 32942630, 2020). "Several CTAs of our panel, such as the MAGE-family members, CTAG1B, TSPY1, and CAGE1, are functionally involved in tumorigeneses and cancer progression by modulating gene expression, regulating mitosis, and tumorigenic signaling." (PMID 34065388, 2021).
CAGE1 also shares sentences with these, for which no sentence is quoted: infection (2 papers); neuroblastoma (2); alcohol use disorder (1); colorectal cancer (1); COVID-19 (1); diabetes (1); esophageal squamous cell carcinoma (1); glioma (1); head and neck squamous cell carcinoma (1); hepatocellular carcinoma (1); leukemia (1); lung carcinoma (1); melanoma (1); metastatic cancer (1); metastatic tumors (1); migraine (1); multiple myeloma (1); periodontitis (1); renal cell carcinoma (1); thrombotic microangiopathy (1).